MAPK8 (mitogen-activated protein kinase 8)
Diseases named in the same sentence as MAPK8 in open-access papers (continued):
Sharing a sentence is not in itself a finding about the gene and the disease.
invasive breast carcinoma (3 papers, 2021 to 2025). A carcinoma that infiltrates the breast parenchyma. "We used a commercially available peptide array in combination with siRNA-based functional validation and identified the kinases IKBKE and MAPK8 as mechano-regulated proteins critical for the matrix stiffness-induced phenotypic switch from DCIS to invasive breast cancer." (PMID 40468448, 2025).
polycystic ovary syndrome (3 papers, 2021 to 2025). A disorder that manifests as multiple cysts on the ovaries. "It is speculated that MAPK8 is one of the therapeutic targets for polycystic ovary syndrome." (PMID 33623786, 2021).
prion disease (3 papers, 2020 to 2023). A transmissible disease that is caused by a protein that is able to induce abnormal folding of normal cellular proteins, leading to characteristic spongiform brain changes, which are associated with neuronal loss without an inflammatory response. "Synaptic proteins, including SNAP-25 and syntaxin 1A/1B, as well as signaling proteins, including calcium–calmodulin protein kinase 4 and mitogen-activated protein kinases (such as MAPK8), showed decreased expression in prion disease." (PMID 36378750, 2022).
uveitis (3 papers, 2015 to 2021). An inflammatory process affecting a part of or the entire uvea. "Therefore, such identified gene MAPK8 may also be a specific uveitis associated gene, corresponding with previous studies and publications." (PMID 30349554, 2018). "Early in 2014, a systematic study on tumor stroma confirmed that MAPK8 contribute to the pathogenesis of a typical tumor complication, uveitis, corresponding with our prediction." (PMID 30349554, 2018). "MAPK8 (ENSP00000353483) was inferred to be potential uveitis-related gene, participating in the specific pathogenesis of such disease." (PMID 30349554, 2018).
essential hypertension (2 papers, 2020 to 2022). Hypertension that presents without an identifiable cause. "Among them, AGTR1, AKT1 with puerarin, EDNRA with tanshinone IIA, MAPK14 with daidzein, MAPK8 with ursolic acid, and CHRM2 with cryptotanshinone all have a strong correlation with GJD in the treatment of primary hypertension." (PMID 36046450, 2022). "The research uncovered that the key active ingredients of GJD in managing primary hypertension are puerarin, tanshinone IIA, daidzein, ursolic acid, and cryptotanshinone, which are mainly expected to contain a regulatory function in conjunction with AGTR1, AKT1, EDNRA, MAPK14, MAPK8, and CHRM2." (PMID 36046450, 2022).
lymph node metastasis (2 papers, 2006 to 2025). "Increased expression of MAPK8 was correlated with the presence of lymph node metastasis." (PMID 41515982, 2025). "Higher levels of MAPK8 and MAP2K7 gene expression were observed in patients with lymph node metastases (number 1–3) compared to patients without lymph node involvement (p = 0.0382; p = 0.0079)." (PMID 41515982, 2025).
medullary carcinoma (2 papers, 2021). "In spontaneous medullary carcinoma in 7M rats, the expression level of Mapk8 was increased, and the expression levels of two other genes, Ulk1 and Wipi1, were decreased." (PMID 34580369, 2021).
myelofibrosis (2 papers, 2022). A partial or complete replacement of the bone marrow stroma by fibrous tissue. "To determine whether JNK1 or JNK2 selectively contributes to TGF-β–induced myelofibrosis, we used CRISPR/Cas9 gene editing to delete Mapk8 (JNK1) or Mapk9 (JNK2) in MSCs." (PMID 35439167, 2022).
preeclampsia (2 papers, 2021 to 2024). Preeclampsia is a hypertensive disorder of pregnancy that is characterized by new-onset hypertension with proteinuria presenting after 20 weeks of gestation, and depending on mild or severe forms may initially present with severe headache, visual disturbances, and hyperreflexia. "A recent study has suggested that the oxidative stress environment in preeclampsia causes an increase in de novo synthesis of ceramides, resulting in increased autophagy in trophoblast, by activating the MAPK8/JNK1 pathway which frees Beclin-1 to initiate autophagy." (PMID 34805141, 2021).
pulpitis (2 papers, 2019 to 2023). Inflammation of the dental pulp. "A miR called miR-584, which specifically inhibits MAPK8, was also found to be up-regulated in pulpitis." (PMID 36890871, 2023).
Constipation (1 paper, 2022). Infrequent or difficult evacuation of feces. "Furthermore, the network pharmacology analysis showed that Akt1, Stat3, Mapk8, Hsp90aa1, Cat, Alb, Icam1, Sod2, and Gsk3b can be regarded as the core anti-constipation targets." (PMID 35408632, 2022).
Ehlers-Danlos syndrome (1 paper, 2020). The Ehlers–Danlos syndromes (EDS) are a clinically and genetically heterogeneous group of heritable connective tissue disorders (HCTDs) characterized by joint hypermobility, skin hyperextensibility, and tissue fragility. "Very recently, AD germline mutations in the MAPK8 gene encoding the kinase JNK1 have been reported in a family with a combination of CMC and a previously undescribed form of connective tissue disorder resembling Ehlers-Danlos syndrome." (PMID 32625202, 2020).
medulloblastoma (1 paper, 2010). A malignant, invasive embryonal neoplasm arising from the cerebellum. "However, mRNA transcripts for components of the PI-3 kinase enzyme complex, Pik3r3 and Pik3cb, and downstream targets of PI-3 kinase signaling, Mapk8 (Jnk) and Frap1 were up regulated 2.8, 1.9, 1.5, and 1.2-fold, respectively in Pten deficient medulloblastomas." (PMID 20520772, 2010).
Ovarian cyst (1 paper, 2021). The presence of one or more cysts of the ovary. "Our result indicated that Jingshu granules may exert a medicinal effect by targeting the MAPK8 and CDK1 of the progesterone-mediated oocyte maturation signaling pathway in ovarian cysts." (PMID 33623786, 2021).
small intestinal tumors (1 paper, 2025). "In addition, MAPK8-deficient mice spontaneously produce small intestinal tumors." (PMID 40369663, 2025).
cancer (1,059 papers, 2001 to 2026). A tumor composed of atypical neoplastic, often pleomorphic cells that invade other tissues. "MAPK1-3 are targeted by oncology drugs such as dordaviprone and ulixertinib, which are actively being explored in cancer treatment, while MAPK8 is implicated in neuropathic pain." (PMID 41049755, 2025). "MAPK8 that plays a critical role in proliferation, differentiation and apoptosis and MAPK8 activity has been implicated in a range of human diseases including cancer, neurological and inflammatory conditions." (PMID 25207642, 2014). "Two genes (CLU, MAPK8) for which expression was suppressed upon GCS knock-down were also reported to promote cancer platinum-resistance." (PMID 40507922, 2025). "Network pharmacology identified 427 potential targets for 12 bioactive alkaloids, with core targets (PIK3CA, PIK3CD, MAPK8, and JAK2) implicated in cancer-related pathways such as PI3K-Akt signaling." (PMID 41169715, 2025). "Mitogen-activated protein kinase 8 (MAP3K8) is a vital component of the MAPK pathway and is associated with the development and progression of various cancers." (PMID 36768307, 2023). "The expression of MAPK8 was significantly different among different stages in cancers KIRC, THCA, COAD, OV, CESC, and ACC." (PMID 35242279, 2022). "MAPK8/JNK1 activation favors cancer proliferation and enhances stem cell-like features of cancer cells." (PMID 35317831, 2022). "Multiple molecular pathways have been reported to regulate cell fate in cancer cells including MAPK8/JNK1/c-Jun N-terminal kinase (mitogen-activated protein kinase 8)." (PMID 35317831, 2022). "We also found that the hub genes (e.g., MAPK8, EGF, FALGDS, CCND1, MYC) in this network have been linked to cancer in wide literature reports." (PMID 31080457, 2019). "On the one hand, OA induces protective autophagy via MAPK8 and mechanistic target of rapamycin (mTOR) pathway activation in various cancer cells." (PMID 29636527, 2018). "Of interest, many of the identified candidate proteins belong to protein families that already have cancer‐associated members (such as MCM6 and MCM7 proteins, MAPK8, or CDC7)." (PMID 29572294, 2018). "MAPK8, MAP kinase family, is associated with cell proliferation, apoptosis and differentiation and was confirmed to be associated with a variety of cancers." (PMID 29340088, 2017). "MAPK8 has been shown to inhibit apoptosis though Bad which can also induce glycolysis, a common trait seen in nearly all cancers." (PMID 25207642, 2014). "The defective MAPK8 has also been involved in several diseases, for instance, DM and cancer." (PMID 40572705, 2025). "In addition, silencing MAPK8 expression reduced cancer cell migration and invasion abilities in ccRCC (P < 0.05)." (PMID 36106411, 2022). "Recent investigations have documented that MAPK8 is activated in cancer progression." (PMID 36106411, 2022). "The role of MAPK8 is rather controversial and seems to depend on the type of cancer." (PMID 34199510, 2021). "Furthermore, we discovered that some of the predicted target genes of Oroxylum indicum were associated with cancer, such as EGFR, PIM1, ESR1/2, and MAPK8/10." (PMID 32733583, 2020). "MAPK8 has been shown to interact with MYC which is frequently observed in numerous human cancers." (PMID 31080457, 2019). "MAPK8, ranked 122th and 431th by MaxMIF with HumanNet and STRINGv10, is a key kinase interacting with other kinases involved in the etiology of many cancer types." (PMID 30250803, 2018). "This target gene might be helpful in cancer therapy, because MAPK8 played a critical role in blunts apoptosis in cancer cells through autophagy." (PMID 26599861, 2015). "Additionally, MAPK8 stress signaling is hyper-activated in fibroblasts residing in high density breasts and tumor stroma where it contributes to fibrosis, inflammation, and the maintenance of cancer stem cell traits." (PMID 40468448, 2025).
cancer (continued). "Therefore, we hypothesized that MYPT1 may inhibit N‐cadherin expression, which influences the cancer cell metastasis, by inhibiting the expression of MAPK8." (PMID 36106411, 2022). "Therefore, it could be deduced that the differential compounds might help to treat cancer by acting on MAPK8 and HIF1A." (PMID 34335821, 2021). "Interestingly, all four target genes were covered, or at least partially covered, by the five signaling pathways identified: BCL2L1 and IGF1R are involved in PI3K-Akt signaling, IGF1R and MAPK8 in FoxO signaling, IGF1R and FAS in proteoglycans in cancer, and MAPK8 and FAS in MAPK signaling." (PMID 30497474, 2018). "ID1 and ID3, associated with cell differentiation, angiogenesis and reported to be increased in several cancers; MAPK8 associated with cell cycle control and cell differentiation and CDC6 a protein involved in DNA replication and which has been implicated in EMT and cancer development." (PMID 25207642, 2014). "Higher levels of MAPK8 and MAP2K4 gene expression were most frequently correlated with the lowest stage of cancer (stage 1 compared to stage 4) (p = 0.0036; p = 0.0339)." (PMID 41515982, 2025). "After assessing the mRNA expression levels of selected genes, we assessed the expression of MAP2K4, MAP2K7, MAPK8, and MAPK9 proteins in cancer and normal colon tissue using images from the Human Protein Atlas." (PMID 41515982, 2025). "Of these DEGs, 6 (EGFR, GATA3, DIABLO, CFLAR, RIPK3, and MAPK8) were repressed, while (ZBP1, PLK1, SPATA2, BCL2, ALK, FASLG, TNFRSF21, and LEF1) were upregulated in cancer cases." (PMID 35610275, 2022). "Subsequently, we selected an enriched pathway (hsa05200: pathways in cancer) and intersected with the top 10 hub genes, and we showed that there are 4 overlapping genes (AKT1, MAPK8, AR, and MDM2)." (PMID 33511213, 2021). "Surprisingly, BCL2L1, E2F1, HRAS, MAPK8, MITF, RELA, and SP1 were all found in the mitophagy and cancer pathways." (PMID 34262589, 2021). "Genes MAP 3 K2, MAP 3 K7, MAP 3 K18, MAPK8 and MAPK9 in the pathway, which were responsible for DNA damage or apoptosis, were all upregulated by melatonin treatment in four cancer cell lines." (PMID 32689938, 2020). "MAPK signalling pathway (JUN, RAC1, MAPK8, MYC and FOS) and transcriptional misregulation in cancer (CDKN1A, MYC and FOXO1)." (PMID 32457348, 2020). "Four target genes (BCL2L1, IGF1R, MAPK8, and FAS) and 5 signaling pathways (PI3K-Akt, FoxO, MAPK, pathways in cancer, and proteoglycans in cancer) were identified." (PMID 30497474, 2018). "C-Jun N-terminal kinase (JNK; MAPK8) regulates a wide range of targets in the progression and metastatic cascade of cancer cells including proliferation, migration, attachment and MMP-expression." (PMID 26293674, 2015). "MAP2K7 and MAPK8 may promote disease progression and metastasis, whereas MAPK9 and MAP2K4 may be more protective at certain stages of cancer development." (PMID 41515982, 2025). "The other identified kinase, MAPK8, also known as c-Jun N-terminal kinase 1 (JNK1), may play a dual and context-dependent role in cancer, with either tumor promoter or tumor suppressor properties depending on the cancer type and cellular environment." (PMID 40468448, 2025). "Besides, previous studies have shown that TNFSF10 can induce autophagy through the MAPK8 activation pathway of TRAF2 and RIPK1, which in turn blunts the apoptosis of cancer cells." (PMID 38375157, 2024). "Our study suggests that TREM1, MAPK1, MAPK8, CTSB, MIF, and DPP4 proteins may be targeted by compounds in medicinal plants for their anti-cancer effects." (PMID 37454152, 2023). "Notably, BCL2L1, E2F1, HRAS, MAPK8, MITF, RELA, and SP1 were found in both mitophagy and cancer pathways." (PMID 34262589, 2021).
cancer (continued). "In addition, hsa-mir-106b-5p also targets genes that play an important role in immunity such as APP, VEGFA, KAT2B, MAPK8, and AGO1 and this miR-mRNA binding allows post-transcription disruption of these genes to influence cancer development." (PMID 33773548, 2021). "Network analysis indicated that main targets of main active components of TWH were target genes such as VEGFA, MAPK8 and CASP3, which are involved in the regulation of cancer pathway, TNF signal pathway, hepatitis B pathway, apoptosis pathway, NF-kappa B signal pathway and so forth." (PMID 32293395, 2020). "The target genes (MAPK8, RPS6KA2) of Lnc_002363 and Lnc_003503 were significantly enriched in the MAPK signaling pathway; this pathway is related to embryonic development, cell proliferation, division, inflammation, cancer and so on65,66." (PMID 32868811, 2020).
tumor (984 papers, 2004 to 2026). "These genes are known to be implicated in proliferation (MAPK8), metastatic diffusion of tumor cells (ITGB1), drug resistance (ANXA1), coagulation (ANXA3, ANXA5) or inflammation (HPGD, NFKB1)." (PMID 29228619, 2017). "Therefore, increased tumor chemo-resistance of NSCLC caused by MAPK8 expression elevation could possibly be explained by enhanced tumor cellular autophagy, once more mechanistic studies were performed to further confirm such putative link." (PMID 33593390, 2021). "This demonstrates that MAPK8 plays different promotional or inhibitory roles in different tumor cells or tissues." (PMID 40369663, 2025). "Patients with low MAP2K4, MAP2K7 or MAPK8 expression or high MAPK9 or JUN in their tumours had greater metastatic frequency following tamoxifen treatment." (PMID 40826108, 2025). "In the B16-F10 melanoma model, the autophagy-critical gene Beclin1 induces substantial infiltration of functional NK cells into the tumor bed by activating the MAPK8/JNK-JUN/c-Jun signaling pathway, significantly inhibiting tumor growth." (PMID 41246345, 2025). "An analysis of the underlying mechanism identified a total of 21 interacting proteins implicated in tumor formation, and among these, AKT1, CDK4, GNB2, and MAPK8 were confirmed at both gene and protein levels." (PMID 39336799, 2024). "IL-8/CXCL8 was found to be regulated by JNK/MAPK8 in colon cancer and became a downstream signal pathway of tumor regrouping induced by necroptosis." (PMID 35237304, 2022). "Secondly, influence of circMED13L_012/miR-433-3p/MAPK8 on the apoptosis and cell cycle of tumor cells was missing in this study." (PMID 33593390, 2021). "Further experiments indicated that circMED13L_012 promoted malignant behavior of NSCLC tumor cells by targeting MAPK8 through modulation miR-433-3p expression." (PMID 33593390, 2021). "These genes included those that have been reported to be associated with the biological behaviour of tumour cells (NTRK2, MAPK8, BCOR, and PIK3R1 genes)." (PMID 31034520, 2019). "Lastly, expression of C-jun amino-terminal kinase interacting protein 1 (MAPK8ip1), a negative regulator of MAPK8 (c-jun amino-terminal kinase), was upregulated 6.9-fold in DC-tumor hybrid cells." (PMID 26605345, 2015). "High breast density displays upregulated MAPK8 activity in fibroblasts and the tumor stroma." (PMID 40468448, 2025). "Furthermore, we found that the anti-tumor effect induced by menadione in CRC cells was mediated through a key gene: MAPK8." (PMID 40872536, 2025). "MAPK8 activation remodels the tumor microenvironment, promoting metastasis and therapy resistance." (PMID 40468448, 2025). "MAPK8 (encoding JNK1) may play a key role in promoting the invasive and migratory potential of tumor cells." (PMID 41515982, 2025). "TNFSF10-induced autophagy was found to be cytoprotective by inhibiting MAPK8 which could improve the sensitivity of tumor cells to targeted drugs." (PMID 36959587, 2023). "MAPK8 can increase the tumor cell's resistance to the insulting condition." (PMID 35821262, 2022). "Furthermore, bioinformatics analysis confirmed that MAP2K7 and MAPK8 appear to promote tumor aggressiveness and metastasis, whereas MAPK9 and MAP2K4 may have a protective or regulatory role in early stages of the disease." (PMID 41515982, 2025). "Data from the Human Protein Atlas revealed differential protein expression of MAP2K4, MAP2K7, MAPK8, and MAPK9 between tumor and normal colon tissues; notably, MAPK8 protein expression did not correspond to the mRNA-level findings." (PMID 41515982, 2025).